CYTH2 (cytohesin 2)
Description:
Acts as a guanine-nucleotide exchange factor (GEF). Promotes guanine-nucleotide exchange on ARF1, ARF3 and ARF6. Activates ARF factors through replacement of GDP with GTP (By similarity). The cell membrane form, in association with ARL4 proteins, recruits ARF6 to the plasma membrane. Involved in neurite growth (By similarity).
Synonyms: ARNO; PSCD2; PSCD2L; CTS18.1; Sec7p-L; Sec7p-like; cytohesin-2; CTS18; SEC7L
Tractability: Small molecule: a structure with a bound ligand is known. Antibody: UniProt places it where antibodies can reach, with high confidence; its Gene Ontology location is reachable by antibodies, with high confidence; the Human Protein Atlas places it where antibodies can reach. PROTAC: ubiquitination databases record sites on it; its protein half-life has been measured.
Chemical probes: SecinH3
Gene: Protein-coding gene on chromosome 19 (48,469,208 to 48,482,314, forward strand). Ensembl gene ENSG00000105443.
Subcellular location: Cell membrane; Cytoplasm; Cell projection; Cell projection, growth cone; Cell junction, tight junction; Cell junction, adherens junction
Subcellular location (Human Protein Atlas): Cytosol; Golgi apparatus; Plasma membrane
Pathways (Reactome):
Vesicle-mediated transport: Intra-Golgi traffic
Gene Ontology:
Molecular function: protein binding; guanyl-nucleotide exchange factor activity; inositol 1,4,5 trisphosphate binding
Biological process: actin cytoskeleton organization; endocytosis; regulation of ARF protein signal transduction
Cellular component: cytoplasm; cytosol; plasma membrane; Golgi membrane; membrane; adherens junction; bicellular tight junction; growth cone
Genetic constraint (gnomAD): Loss-of-function variants: 24 observed, 56.55 expected, observed/expected ratio (o/e) 0.42, 90% interval 0.31 to 0.6. The upper end of that interval is the gene's LOEUF score, 0.6, which puts it in group 2 of 6, group 1 being the genes least tolerant of losing a copy. Missense variants: 378 observed, 555.1 expected, observed/expected ratio (o/e) 0.68, 90% interval 0.62 to 0.74. Synonymous variants: 221 observed, 219.86 expected, observed/expected ratio (o/e) 1.01, 90% interval 0.9 to 1.12.
Homologues: Orthologues: macaque CYTH2 (100% identical), dog CYTH2 (99% identical), mouse Cyth2 (99% identical), pig CYTH2 (99% identical), guinea pig CYTH2 (98% identical), rat Cyth2 (98% identical), chimpanzee CYTH2 (97% identical), rabbit CYTH2 (92% identical), tropical clawed frog cyth1 (92% identical), zebrafish cyth2 (88% identical), Drosophila melanogaster Sec71 (39% identical), Caenorhabditis elegans agef-1 (33% identical), and 4 more. Paralogues in human: CYTH1 (82% identical), CYTH3 (79% identical), CYTH4 (68% identical), ARFGEF2 (43% identical), ARFGEF1 (43% identical), GBF1 (37% identical), IQSEC1 (33% identical), IQSEC2 (30% identical), IQSEC3 (29% identical), MON2 (25% identical), PSD (25% identical), PSD3 (24% identical), and 3 more.
Diseases named in the same sentence as CYTH2 in open-access papers:
CYTH2 is named in the same sentence as 27 diseases in open-access papers, as found by Europe PMC text mining. Sharing a sentence is not in itself a finding about the gene and the disease. The quoted sentences say what the papers report.
breast carcinoma (4 papers, 2012 to 2023). "It suggests that upregulated DPP9, LRRC20 and TTBK2 together with downregulated TTC17, ZNF75D and CYTH2 may play pivotal role in the orchestrated adaptive homing of metastatic breast cancer cells in bone niche." (PMID 35685372, 2022).
colorectal cancer (3 papers, 2013 to 2021). A primary or metastatic malignant neoplasm that affects the colon or rectum. "In vitro studies on colorectal cells pointed out that cytohesin 2 blockade associated with a decreased cell proliferation, migration, and invasion of tumor cells, indicating cytohesin 2 as a potential therapeutic target in colorectal cancer." (PMID 34063287, 2021). "This study found that ARNO (cytohesin-2), an activator of the EGF and IGF-I pathways, was more highly expressed in colorectal cancer tissue than in benign adjacent colorectal tissue." (PMID 24618737, 2014).
diabetes (1 paper, 2025). "SecinH3, a specific inhibitor of cytohesin‐2 (ARNO), effectively suppresses Arf6 activation by targeting its Sec7 domain, showing potential applications in diabetes and prostate smooth muscle dysfunction." (PMID 41020039, 2025).
hepatocellular carcinoma (1 paper, 2020). A malignant tumor that arises from hepatocytes. "Moreover, the increased expression of ARF6-CD147 signaling components, like Cytohesin 2/ARNO, an ARF6 GEF and Rac1 were associated with poor overall survival of hepatocellular carcinoma patients." (PMID 32426352, 2020).
lung fibrosis (1 paper, 2006). "Because MAP kinases are activator signals for lung fibroblasts, we suggest that cytohesin-2 might participate in the development and/or progression of lung fibrosis in SSc patients through the activation of the MAP kinase signaling pathways in lung fibroblasts." (PMID 17044913, 2006).
ovarian carcinoma (1 paper, 2023). A malignant neoplasm originating from the surface ovarian epithelium. "In ovarian cancer patients, CYTH2 mRNA was increased in the tumour compared with normal epithelium in both independent data sets of LCM tumours, whereas stromal CYTH2 levels were inconsistent across data sets (Fig EV5H and I)." (PMID 37577760, 2023).
Ssc (1 paper, 2021). "The results of the current study confirmed circulatory calumenin, S100A6 and cytohesin 2 as biomarkers for SSc patients." (PMID 34063287, 2021).
Telangiectasia (1 paper, 2021). Telangiectasias refer to small dilated blood vessels located near the surface of the skin or mucous membranes, measuring between 0.5 and 1 millimeter in diameter. "Higher serum cytohesin 2 levels were observed in patients with telangiectasia presence (median 45.11 ng/mL (19.53) versus 40.46 ng/mL (11.68), Mann Whitney U test, p = 0.025)." (PMID 34063287, 2021).
tumor (5 papers, 2013 to 2023). "Both the CYTH2 GEF and AGAP1 GAP mRNAs were elevated in tumour tissue in a number of data sets; however, CYTH2 contribution is complicated by poor outcome being specifically conferred by the PIP3‐associating CYTH22G isoform." (PMID 37577760, 2023).
CYTH2 also shares sentences with these, for which no sentence is quoted: cancer (2 papers); infection (2); Salmonella Infections (2); adenocarcinoma (1); Arthritis (1); asthma (1); autoimmune disease (1); colorectal adenocarcinoma (1); inflammatory bowel disease (1); joint disease (1); liver cancer (1); lung carcinoma (1); osteoarthritis (1); osteosarcoma (1); pancreatic cancer (1); prostate carcinoma (1); rhinitis (1); vasculitis (1).